HBA1 (hemoglobin subunit alpha 1)
Diseases named in the same sentence as HBA1 in open-access papers (continued):
Sharing a sentence is not in itself a finding about the gene and the disease.
pterygium (2 papers, 2020 to 2021). A wedge-shaped fibrovascular lesion arising from the bulbar conjunctiva and extending to the cornea. "In this study, HBA1, HBA2, and HBB were among the top 25 upregulated DEGs in pinguecula and top 25 downregulated DEGs in pterygium." (PMID 34769520, 2021). "For example, hemoglobin genes HBA1, HBA2, and HBB were among the top 25 upregulated genes in pinguecula and top 25 downregulated genes in pterygium." (PMID 34769520, 2021). "From the results of RNA-Seq, LCN1, LTF, SCGB2A1, HBA1 (hemoglobin subunit alpha 1) and HBA2 (hemoglobin subunit alpha 2) ranked as the top five DEGs in the comparison between pterygium and normal tissues." (PMID 32411530, 2020). "The mRNA expressions of SCGB2A1, LTF and LCN1 were significantly decreased in pterygium tissues compared with normal control tissues, while the mRNA levels of HBA1 and HBA2 were higher in the pterygium tissues than in the control tissues." (PMID 32411530, 2020).
Stroke (2 papers, 2018 to 2021). Sudden impairment of blood flow to a part of the brain due to occlusion or rupture of an artery to the brain. "Mutations in HBA1 can cause myocardial infarction, stroke, coronary heart disease, and HF." (PMID 34774109, 2021).
abdominal aortic aneurysm (1 paper, 2023). Enlargement and ballooning of the vessel that supplies arterial blood to the abdomen, pelvis and legs. "HBA1 and HBA2 both encode alpha subunits of hemoglobin and have also been found to be increased in abdominal aortic aneurysms." (PMID 36836499, 2023). "For example, several (5/39) of the significant genes (including LPL, IFI44L, ACKR2, HBA1, and HBA2) have also been found to be differently expressed in abdominal aortic aneurysms." (PMID 36836499, 2023).
acute leukemia (1 paper, 2025). A clonal (malignant) hematopoietic disorder with an acute onset, affecting the bone marrow and the peripheral blood. "The results of our study suggest that the increased expression of ACTB and the molecular interplays involving “HBA1&HBB," “HBB&HBA1," “IGKV1-5&IGHV4-31," “IGHV4-31&IGKV1-5," “HLA-DRA&CD74" and “ACTB&ACTB" might contribute to the progression of acute leukemia." (PMID 40338916, 2025). "Furthermore, the suppression of ACTB and the molecular interactions involving pairs such as “HBA1&HBB", ”HBB&HBA1", “IGKV1-5&IGHV4-31", “IGHV4-31&IGKV1-5", “HLA-DRA&CD74", and “A CTB&ACTB" might provide essential insights into unraveling the intricate mechanisms of acute leukemia." (PMID 40338916, 2025).
Adrenal insufficiency (1 paper, 2019). Insufficient production of steroid hormones (primarily cortisol) by the adrenal glands. "The lowest HbA1 C (one case) was observed in patient on gliclazide, suffering from hemolytic anemia, periodically on steroids (without this treatment prior to hospitalization), with liver failure, and suspicion of secondary adrenal insufficiency." (PMID 31477024, 2019).
asthma (1 paper, 2021). "In bronchial epithelial cells collected by bronchoscopic brush biopsy, the expression of hemoglobin genes (HBA1, HBA2, HBB and HBD) was strongly correlated with Pre-bronchodilator FEV1 PP in patients with asthma enrolled in SARP I&II but not in controls." (PMID 34326365, 2021).
atherosclerosis (1 paper, 2024). A disease characterized by the build-up of fatty material and calcium deposition in the arterial wall resulting in partial or complete occlusion of the arterial lumen. "Finally, miR-199b-5p upregulation was predicted to lead to the activation of HbA1c (HBA1/HBA2) through the inhibition of surfactant protein A1 (SFTPA1), thus resulting in a predicted association with enhanced atherosclerosis progression." (PMID 39125657, 2024).
avian influenza (1 paper, 2020). Infection of domestic and wild fowl and other birds with influenza A virus. "In conclusion, HBA1 and HBA2 can be used to diagnose avian influenza in place of traditional diagnostic methods, because they can quickly and accurately distinguish between the avian influenza subtypes." (PMID 32731467, 2020).
cervical cancer (1 paper, 2013). A primary or metastatic malignant neoplasm involving the cervix. "Compared to normal cervix epithelium, cervical cancer samples showed a significant elevation in the expression of HBA1 and HBB genes." (PMID 23349856, 2013). "In order to validate the potential role of Hgb in human cervical carcinoma, the expression levels of HBA1 and HBB were investigated in 20 cervical cancer specimens and 10 normal cervix tissue samples by qRT-PCR analysis." (PMID 23349856, 2013). "Consistent with the microarray dataset, qRT-PCR analysis showed that the expression of HBA1 and HBB was significantly higher in cervical cancer tissues than in normal cervix tissues." (PMID 23349856, 2013). "Firstly, RT-PCR experiment was performed to determine the expression levels of HBA1 and HBB genes in 20 cervical cancer samples." (PMID 23349856, 2013). "RT-PCR analysis using human blood cell RNA as a positive control showed the presence of the mRNA for the HBA1 and HBB chains of human Hgb in cultured cervical cancer cells." (PMID 23349856, 2013). "In summary, these results suggested that both HBA1 and HBA1/HBB overexpression may have an antioxidant effect via scavenging of ROS, thus protecting cervical cancer cells against oxidative stress-induced damage." (PMID 23349856, 2013). "As Hgb is likely to act as heterotetramer of two different subunits, we took advantage of co-immunoprecipitation experiments to interrogate whether HBA1 and HBB expression in cervical cancer are able to form heterodimers." (PMID 23349856, 2013). "Double-immunostaining using polyclonal antibodies with cross-reactivity against HBA1 and HBB and an antibody specific for p16INK4A, a specific marker of cervical cancer used for cytology and histological diagnosis, showed the co-localization of Hgb with p16INK4A in cervical cancer tissues." (PMID 23349856, 2013). "Taking advantage of commercial andibodies produced against human HBA1 and HBB, immunofluorescence analysis was performed to examine the localization of the Hgb protein in SiHa cells, which showed a similar cytoplasmic staining pattern of the HBA1 and HBB forms as that of cervical cancer tissues." (PMID 23349856, 2013). "qRT-PCR analysis showed that Hgb-α- (HBA1) and Hgb-β-globin (HBB) gene expression was significantly higher in cervical carcinoma than in normal cervical tissues, whereas the expression of hematopoietic transcription factors and erythrocyte specific marker genes was not increased." (PMID 23349856, 2013). "The fact that the expression level of HBA1 in cervical cancer cell lines is higher than that of HBB suggests that multiple bioactive molecules, not only the heterodimer forms but also monomer or homodimer forms of the HBA1 protein may be present at the same time in cervical cancer cells." (PMID 23349856, 2013).
endometriosis (1 paper, 2024). The growth of functional endometrial tissue in anatomic sites outside the uterine body. "In the high JUP group, we identified several downregulated genes in the PBMCs from endometriosis patients, including HBB, HBA1, HBA2, RGPD2, CH25H, LTB, IFIT2 and JUN." (PMID 39684780, 2024). "Comparison between participants without endometriosis (n = 5) and participants with endometriosis (n = 4) with high serum JUP values (>220 ng/mL) identified nine DEGs (HBB, HBA1, HBA2, and RGPD2 in CD14+ monocytes; CH25H, HBB, LTB, and KLRC1 in γδt; IFIT2 in NK-CD56bright and JUN in Treg)." (PMID 39684780, 2024).
glioma (1 paper, 2021). A benign or malignant brain and spinal cord tumor that arises from glial cells (astrocytes, oligodendrocytes, ependymal cells). "Spot E also contains genes related to hemoglobin function such as HBA1, neuroglobin (NGB), and SRBP1, which upregulate in glioma tissues under hypoxic conditions." (PMID 34206856, 2021).
hepatocellular carcinoma (1 paper, 2023). A malignant tumor that arises from hepatocytes. "Furthermore, the overexpression of hemoglobin (HBA1 and HBB) in the rat renal mesangial and human hepatocellular cancer cell lines alleviates H2O2-induced oxidative stress, leading to enhanced cell viability under oxidative stress conditions." (PMID 38067210, 2023).
Hypoglycemia (1 paper, 2022). A decreased concentration of glucose in the blood. "Low HbA1 suggests increased risk of hypoglycemia, possibly associated with liver disease and increased insulin resistance." (PMID 35977993, 2022).
macrosomia (1 paper, 2022). "In this study, we constructed a nomogram model based on the risk factors of macrosomia including maternal BMI before pregnancy, parity, a prior macrosomic newborn, preexisting GDM/DM, the levels of HbA1 and TC in the first trimester." (PMID 35513792, 2022). "In the study, the nomogram for predicting the risk of macrosomia was established based on the risk factors identified by the multivariate logistic regression analysis including prepregnancy BMI, parity, history of macrosomia, history of GDM/DM, first-trimester HbA1 and TC levels." (PMID 35513792, 2022).
macular degeneration (1 paper, 2025). Loss of vision in the central portion of the retina (macula), secondary to retinal degeneration. "•Proteins linked to macular degeneration (CA1, CA2, HBA1) and PRP treatment (APOB, CST6) were identified." (PMID 40118382, 2025). "Additionally, proteins associated with macular degeneration (CA1, CA2, and HBA1) were uncovered, providing new insights into overlapping mechanisms between DR and other retinal diseases." (PMID 40118382, 2025).
male infertility (1 paper, 2024). The inability of the male to effect fertilization of an ovum after a specified period of unprotected intercourse. "Furthermore, the ICSI-associated DEGs MAP1B, HBA1, EPHX1, HBB, and HBG2 enriched in response-to-toxic-substance pathway are also interesting (FDR-corrected q-value < 0.05), considering that environmental exposures have been associated with male infertility in previous studies." (PMID 39702541, 2024).
multiple system atrophy (1 paper, 2017). Multiple system atrophy (MSA) is a neurodegenerative disorder characterized by autonomic failure (cardiovascular and/or urinary), parkinsonism, cerebellar impairment and corticospinal signs with a median survival of 6-9 years. "In addition to PD, altered expression of hemoglobin genes, including HBB, HBA1, and HBA2 have been found in the frontal cortex of multiple system atrophy patients, an atypical parkinsonian disorder that is often misdiagnosed as PD." (PMID 28424608, 2017).
osteosarcoma (1 paper, 2024). A usually aggressive malignant bone-forming mesenchymal neoplasm, predominantly affecting adolescents and young adults. "IFITM5, MMP13, PANX3, and MAGEA6 were some of the most overexpressed genes in osteosarcoma samples, while SLC4A1, HBA1, HBB, AQP7 genes were some of the top downregulated genes." (PMID 38966281, 2024). "Similarly, HBA1, HBA2, and HBB were downregulated in osteosarcoma samples." (PMID 38966281, 2024).
pancreatic diseases (1 paper, 2021). "Some of them were upregulated in patients with other pancreatic diseases, such as HBB, HBA1, and KRT16 proteins, while some were upregulated only in PC groups (i.e. ALIX, GPRC5B, SDCBP, and IST1), highlighting their potential diagnostic value." (PMID 34026608, 2021).
prediabetes (1 paper, 2019). "Our study examined the suitability of the IDF-modified criteria that include, according with the prediabetes ADA criterion, an HbA1 level of 5.7% as a cut-off criterion, which would replace FPG as a dysglycemia indicator." (PMID 31805696, 2019).
prion disease (1 paper, 2018). A transmissible disease that is caused by a protein that is able to induce abnormal folding of normal cellular proteins, leading to characteristic spongiform brain changes, which are associated with neuronal loss without an inflammatory response. "However, the analysis of HBB and HBA1/2 mRNA levels in acquired prion diseases patients revealed some differences, suggesting that exogenous prions might exert an impact on Hb metabolism." (PMID 29403351, 2018). "Regarding prion diseases groups, dysregulated HBB and HBA1/2 transcript levels followed different trends depending on the disease type." (PMID 29403351, 2018).
sickle cell disease (1 paper, 2022). Sickle cell anemias are chronic hemolytic diseases that may induce three types of acute accidents: severe anemia, severe bacterial infections, and ischemic vasoocclusive accidents (VOA) caused by sickle-shaped red blood cells obstructing small blood vessels and capillaries. "We studied the association of microRNA-423 with hemoglobin variables HbA1, HbA2, HbF and HbS of the patients with sickle cell disease were compared with the 3 genotypes (AA, AC and CC) of miR-423." (PMID 35735616, 2022).
sleeping sickness (1 paper, 2023). "HBA1, UBE2I, CSNK2A1, RRP12, and HSP90AB1 were highly enriched in African trypanosmiasis (sleeping sickness) than in the dengue viral infection pathway." (PMID 37498862, 2023).
steatosis (1 paper, 2019). Increased lipid within the cytoplasm of cells. "Multivariate analysis showed that steatosis was independently associated with serum miR-33a, ALT, glycaemia and waist circumference, whereas inflammation was independently associated with miR-33a, HbA1 and serum triglyceride levels." (PMID 31703079, 2019).
Wolman disease (1 paper, 2021). Wolman disease represents the most severe manifestation of lysosomal acid lipase deficiency. "Using a similar Cas9/AAV6 approach, Pavani and colleagues targeted the lysosomal acid lipase (LAL) transgene, associated with the LSD Wolman disease, into the alpha-globin loci (HBA1 and HBA2) of healthy donor HSPCs." (PMID 33535527, 2021).
xerostomia (1 paper, 2015). Dryness of the mouth resulting from reduced salivary secretion. "The aim of this study was to evaluate salivary gland dysfunction in patients with DM2, measuring the different levels of metabolic control with the HbA1 test and examining the SFR, pH, protein concentration and xerostomia parameters." (PMID 26535097, 2015).
tumor (13 papers, 2020 to 2025). "The genes with the highest log fold-change of expression in the tumor chunks compared to the dissociated cells were hemoglobin genes (HBA1, HBA2, HBB)." (PMID 37864274, 2023). "Importantly, patients with high tumour HBA1 expression led to poor overall survival supporting our findings in CRLM." (PMID 38492056, 2024). "In addition, we also found that HBA1 was highly expressed in single cells of tumor samples and cancerous mucous cells, and the results of survival analysis show that it is indeed a risk factor." (PMID 35659682, 2022). "We report that histone H4, HBA1, IMPDH2, and two unidentified m/z values (m/z 1305.840 and 1661.060) are more abundant in tumour tissues of CRLM patients with poor survival." (PMID 38492056, 2024). "Meanwhile, restoring HBA1 expression via gene therapy or epigenetic modulation may help counteract the metabolic and hypoxic advantages of HNSCC cells, potentially limiting tumor survival and progression." (PMID 40299352, 2025). "Because both cancer cohorts have no HGB-related clinical data available, we quantified a tumor’s HGB level as the average expression levels of four HGB-related genes (HBA1, HBA2, HBB and HBD)." (PMID 39415833, 2024). "Interestingly, the high abundance identifies were consistent both in the tumor and normal tissues in EESCC and EDAC at the protein level, including HBB, HBA1, HBD, ACTB, ALB, etc.." (PMID 35397555, 2022). "Hemoglobin Subunit Alpha 1 (HBA1) has not been reported much in previous clinical studies on tumor prognosis." (PMID 35659682, 2022). "Hemoglobin subunit beta (HBB) and hemoglobin subunit alpha 1 (HBA1) mRNA levels were significantly upregulated in MBM, although their upregulation in MBM may reflect a hemorrhagic component of the tumor as opposed to a true biological difference." (PMID 37964004, 2023).
cancer (9 papers, 2012 to 2024). A tumor composed of atypical neoplastic, often pleomorphic cells that invade other tissues. "HBB and HBA1 have been demonstrated to be downregulated in several cancers, which is related to cancer cell growth." (PMID 32695162, 2020). "Since we found the idea of a cancer tissue expressing hemoglobin interesting and worth exploring further, we decided to include HBA1 in the immunohistochemistry validation." (PMID 22615549, 2012). "HBB and HBA1 are now anti-metastatic factors in other cancers and the downregulation of these genes may be indicative for enhanced formation of metastases." (PMID 38966281, 2024). "It is worth mentioning that HBA1, S100A8 and S100A9 play important roles in mediating drug resistance in cancer cells, which also provides insights into the mechanism of drug resistance in AML." (PMID 39583114, 2024). "However, the specific contribution of HBA1 in cancer progression is unknown." (PMID 38492056, 2024). "In this regard, HBA1 and HBB present challenging candidates for ROS-targeted cancer therapy due to their known expression in erythrocyte tissues." (PMID 38067210, 2023). "First of all, in analyzing the TCGA and Pancancer_2020 cohorts, we have used the mean expression levels of HBA1, HBA2, HBB and HBD to represent HGB levels of cancer patients, which may not fully reflect blood HGB levels." (PMID 39415833, 2024).
infection (7 papers, 2010 to 2025). The state of being infected such as from the introduction of a foreign agent such as serum, vaccine, antigenic substance or organism. "Genes (Hbb-bt, Hba1/Hba2, and Alas2) involved in hemoglobin biosynthesis and heme homeostasis, on the other hand, were significantly down-regulated in response to infection." (PMID 30857242, 2019). "Meanwhile, we observed that certain biomarkers (SLC7A5, PDE4D, CXCR4, PER1, PIK3R1, HBA1, HBB) were elevated during the pre-infection phase (LTBI), while others (SOCS3, GZMK, HIS1H3B) were upregulated in the post-infection phase (ATB)." (PMID 40589756, 2025). "Cell growth and differentiation (HRASLS2), transport (PNN, SLC4A4, and HBA1), metabolism (SRD5A3), and immune response (SSC4D) involved genes were highly regulated in the early HEV gt3 infection." (PMID 32877413, 2020). "HRASLS2 was found to be upregulated in all three phases and upregulation of HBA1 gene was detected at the early and the peak phases of the HEV gt3 infection." (PMID 32877413, 2020). "Unsurprisingly, HbA1, HbA2 and HbD gene expression was less in ALV-J infected birds, although until now, little has come to light on the molecular relationship between hemoglobin synthesis and ALV infection." (PMID 21637603, 2010).
neurodegenerative disease (1 paper, 2023). A disorder of the central nervous system characterized by gradual and progressive loss of neural tissue and neurologic function. "Expression of this protein in various brain regions (Genecards, HBA1) has been linked to the regulation of oxidative stress and has been identified in various neurodegenerative diseases." (PMID 37425000, 2023).
HBA1 also shares sentences with these, for which no sentence is quoted: phenylketonuria (3 papers); spinal muscular atrophy (3); vitamin D deficiency (3); dyslipidemia (2); G6PD deficiency (2); genetic disorder (2); heart disease (2); hematological disease (2); melanoma (2); pancreatic cancer (2); Wilson disease (2); autoimmune disease (1); autosomal recessive deafness (1); autosomal recessive disease (1); Blepharophimosis (1); breast invasive carcinoma (1); chronic myeloid leukemia (1); colorectal (1); congenital adrenal hyperplasia (1); coronary heart disease (1); cutaneous melanoma (1); diabetic retinopathy (1); dyslipidaemia (1); endothelial dysfunction (1); ependymoma (1); Epicanthus inversus (1); familial candidiasis (1); familial erythrocytosis (1); gastric adenocarcinoma (1); haemolytic anaemia (1).
A further 43 diseases each share a sentence with HBA1 in 1 paper.